MTOR (mechanistic target of rapamycin kinase)
Diseases named in the same sentence as MTOR in open-access papers (continued):
Sharing a sentence is not in itself a finding about the gene and the disease.
Cognitive impairment (continued). "However, mTOR plays an essential role in AD pathogenesis, which contributes to cognitive impairment as well as brain dysfunction, although mTOR inhibition protects the pathogenesis of AD." (PMID 33800526, 2021). "This study aimed to explore whether rapamycin can ameliorate anesthesia/surgery-induced cognitive deficits by inhibiting mTOR, activating autophagy and rising synaptic plasticity-related proteins in the hippocampus." (PMID 33935683, 2021). "Another aspect is that the target of RM, mTOR, is involved in axonal growth, synaptic plasticity, and learning and memory; therefore, a long-lasting RM treatment and mTOR inhibition could induce cognitive defects." (PMID 34025345, 2021). "At this stage, administration of an MTORC1 inhibitor rapamycin for 10 weeks could restore mTOR signaling, decrease Aβ and tau pathology, and ameliorate cognitive deficits (Caccamo, Majumder, Richardson, Strong, & Oddo, 2010)." (PMID 31858697, 2020). "However, in D-Gal induced rodent aging models, ginsenoside Rg1 afforded anti-oxidant and anti-inflammatory effects to prevent cognitive impairment and hippocampal cell senescence, in which the Akt/mTOR signaling was inhibited 34-36." (PMID 32410834, 2020). "Inhibition of mTOR may have the potential to treat age-related synaptic dysfunction and cognitive deficits." (PMID 32382276, 2020). "Early blockade of 5‐HT6 receptor‐operated mTOR signaling could be a novel therapeutic strategy to prevent adult stage‐onset of cognitive deficits in cannabis abusers during adolescence." (PMID 32329240, 2020). "Other studies found that Rg1 could decrease oxidative stress and downregulate Akt/mTOR signaling to attenuate cognitive impairment in mice and senescence of neural stem cells induced by D-gal." (PMID 31915506, 2019). "Indeed, mice treated with dietary TMAO show increased brain aging and cognitive impairment, likely due to increased oxidative stress, mitochondrial dysfunction, and inhibition of mammalian target of rapamycin (mTOR) signaling in the brain." (PMID 30579367, 2018). "In our recent study, we found that mTOR/S6K signalling is over-activated in the brains of diabetic mice and that inhibition of mTOR signalling with rapamycin alleviates the phosphorylation level of hyperphosphorylated tau and prevents the formation of DM-induced cognitive deficits." (PMID 28489581, 2017). "The known antioxidant edaravone could effectively attenuate cognitive impairment; its protective mechanism may be related to its antioxidant and anti-inflammatory effects, as well as its ability to maintain activation of the Akt/mTOR signaling pathway." (PMID 27116382, 2016). "Thus, MTOR p.E1799K can now be classified as a pathogenic GOF mutation that causes megalencephaly and cognitive impairment in humans." (PMID 26542245, 2015). "The activation of mTOR may rescue cognitive impairment, as its up-regulation through GSK3 inhibitors rescued long-term potentiation, a cellular model of synaptic plasticity, in a mouse model of AD." (PMID 25100990, 2014). "Accordingly, activation of mTOR may fulfil a broader role in the cognitive impairment of CNS disorders than hitherto appreciated." (PMID 23027611, 2012). "Collectively, these results indicate that mTOR signalling mediates the cognitive impairments induced by activation of 5-HT6 receptors in PFC in two cognitive paradigms with clear relevance to the impairment of social cognition, attention and episodic memory observed in schizophrenia." (PMID 23027611, 2012). "We then reasoned that enhanced mTOR signalling in the PFC, under the control of 5-HT6 receptors, might underlie cognitive deficits of schizophrenia." (PMID 23027611, 2012). "It was shown that cognitive deficits in VaD rats could be improved through the PI3K/Akt/mTOR signaling pathway, which may be related to the increase in the level of mitophagy and the inhibition of neuronal apoptosis, which attenuated neuronal damage and mitochondrial dysfunction." (PMID 39169952, 2024).
Cognitive impairment (continued). "Furthermore, they ameliorate cognitive impairment caused by chronic cerebral insufficiency, protect against ischemia-induced white matter lesions via the PI3K/Akt/mTOR pathway in the white matter, and facilitate SCI treatment by promoting axonal growth and extension into the lesion site." (PMID 38756705, 2024). "Importantly, we demonstrated that pretreatment with the mTOR inhibitor rapamycin ameliorated surgery‐induced neuronal apoptosis and cognitive impairment by enhancing autophagic removal of abnormal tau hyperphosphorylation and Aβ deposition in the hippocampus of diabetic rats." (PMID 34784444, 2022). "Interestingly, blocking the 5-HT6 receptor-mediated mTOR signal activation may improve neuropathic pain and mitigate complications of cognitive impairment as evidenced in rats." (PMID 35669881, 2022). "Our results confirm that MCE could restore the antioxidant status and improve cognitive impairment in aging mice, inhibit d-gal-induced apoptosis by regulating the PI3K/AKT signaling pathway, and rescue the impaired autophagy caused by mTOR overexpression, thereby exerting an anti-aging effect." (PMID 35889375, 2022). "The main findings from this study were that NNI-362 promoted proliferation and survival of adult-born neural cells associated with reversal of cognitive deficits, without toxic or off-target effects up to 6 weeks of administration, and acts allosterically and downstream of mTOR." (PMID 33436007, 2021). "Likewise, non-physiological mTOR activation underlies cognitive deficits observed in preclinical models of acute cannabis consumption in adulthood and of cannabis abuse during adolescence and those observed in neuropathic pain conditions." (PMID 34576341, 2021). "Thus, this present study suggests that inhibiting excessive activity of mTOR and activating autophagy may provide a restorative method for the treatment of anesthesia/surgery-induced cognitive impairment." (PMID 33935683, 2021). "Moreover, they may be able to restore the circadian rhythm of mTOR activation, which is quite a novel finding in the field of research on metabolic diseases and cognitive impairment." (PMID 34885795, 2021). "Furthermore, THC administration in adulthood did not induce such a prolonged activation of mTOR signaling and associated cognitive deficits." (PMID 32329240, 2020). "Thus, the possible mechanism for melatonin might be alleviating the cognitive impairment induced by isoflurane exposure, which downregulates the proinflammatory cytokines by inhibiting the mTOR pathway in the hippocampus." (PMID 31803045, 2019). "In the present study, a mouse model was employed to determine whether mTOR participates in the pathophysiology of PND by aggravating the hippocampal neuroinflammation and whether melatonin ameliorates the postoperative cognitive impairment by inhibiting the expression of mTOR in the hippocampus." (PMID 31803045, 2019). "miR‐17/20a‐5p promoted activation of the mechanistic target of rapamycin (mTOR) pathway, enhanced synaptic plasticity, and mitigated CCH‐induced cognitive impairment." (PMID 40271743, 2025). "This study was designed to evaluate the effects of liraglutide on hippocampal PI3K/Akt/mTOR signaling and autophagy and its role in the alleviation of high-fat diet (HFD)-induced depressive-like behaviors and cognitive deficits." (PMID 40526304, 2025). "In particular, grape polyphenols have been shown to alleviate cognitive deficits by activating CREB and mechanistic target of rapamycin (mTOR) pathways, promoting synaptic plasticity." (PMID 39458427, 2024). "Mechanistically, THF suppresses the upregulation of PTEN expression, leading to elevated p-Akt and p-mTOR level, promoting the proliferation of NSCs, and subsequently ensures normal neurogenesis after ICH, ultimately alleviating cognitive impairment." (PMID 38729764, 2024).
Cognitive impairment (continued). "In summary, our study demonstrated that a long-term HS diet can lead to cognitive impairment and impair the level of GLP-1R, and then activate mTOR/p70S6K pathway to inhibit autophagy flux." (PMID 38575652, 2024). "Cognitive impairment can be considered as an effect resulting from the activation of multiple signaling pathways, including RAF/MAPK and VEGF/VEGFR2/mTOR, which subsequently affect various cellular processes associated with corticogenesis." (PMID 38023143, 2023). "In APP/PS1 mouse model, TRPML1 has been reported to alleviate cognitive impairment in AD by mediating neuron autophagy and reducing autophagosome accumulation through the PPARγ/AMPK/mTOR signaling pathway." (PMID 35116093, 2022). "Dietary curcumin and resveratrol either reduce mTOR levels to disrupt the C1 complex or inhibit mTORC1 by activating AMPK, thereby inducing autophagy and rescuing cognitive impairment in 2X AD transgenic mice." (PMID 34215308, 2021). "Notoginsenoside Rb1 regulates the Akt-mTOR-PTEN signalling pathway and can alleviate motor and cognitive impairment induced by MCAO in rats." (PMID 34434246, 2021). "Like the mTOR pathway, disruption of the RAS pathway was recurrently shown to correlate with ASD severity and symptoms, cognitive impairments and intellectual disability." (PMID 34828352, 2021). "Isoflurane induces cognitive impairment in aged mouse models by inducing the production of brain cytokines including TNF-α, IL-1β, and IL-6 via suppressing the mammalian target of rapamycin (mTOR) signaling." (PMID 34895041, 2021). "Hence, interference with the IRS1/AKT/mTOR pathway may lead to cognitive impairment." (PMID 32372981, 2020). "Melatonin and rapamycin significantly ameliorated the isoflurane-induced cognitive impairment and also led to a decrease in the melatonin levels as well as the expression levels of TNF-α, IL-1β, IL-6, and p-mTOR in the hippocampus." (PMID 31803045, 2019). "In a traumatic brain injury model, AKT and mTOR were activated after injury and inhibition of AKT and mTOR improved motor and cognitive deficits post-injury." (PMID 29385149, 2018). "In two developmental models of schizophrenia, specifically neonatal phencyclidine treatment and post-weaning isolation rearing, the activity of mTOR was enhanced in the PFC, and rapamycin, like 5-HT6 antagonists, reversed these cognitive deficits." (PMID 23027611, 2012). "Our findings demonstrate that enhancing endogenous irisin via FAE mitigates CCH-induced neuronal apoptosis, microglial activation, cognitive impairment, and affective behavioral deficits by promoting autophagy through the integrin αVβ5/AMPK/mTOR signaling pathway." (PMID 40581647, 2025). "The effects of chronic liraglutide administration (subcutaneous; 300 μg/kg/day for 28 days) were investigated on depressive-like phenotypes, cognitive deficits, and hippocampal phosphatidylinositol 3-kinase (PI3K)/protein kinase B (Akt)/mechanistic target of rapamycin (mTOR)-regulated autophagy." (PMID 40526304, 2025). "Our study does not exclude other ways by which mTOR hyperactivity can contribute to cognitive deficits, but restoring γ-oscillations is a potential target for early-stage AD therapy." (PMID 37163441, 2023). "Retigabine, a drug that opens voltage-gated potassium channels, has been shown to abolish stress-induced cognitive defects; normalize the expression of PGC-1α, β-catenin, and USP2; and alleviate the increase in phosphorylated mammalian target of rapamycin (mTOR) and autophagy components." (PMID 33530560, 2021). "In summary, our results identified that agomelatine could improve cognitive impairment and ameliorate AD-like pathology in APP/PS1 mice via activating DHCR24 signaling and inhibiting Akt/mTOR and Hes1/Notch1 signaling pathway." (PMID 35153715, 2021).
Cognitive impairment (continued). "The sustained activation of mTOR signaling, under the control of 5‐HT6 receptors, elicited in PFC by adolescent THC exposure might induce cognitive deficits in adulthood through different mechanisms." (PMID 32329240, 2020). "On the other hand, during the post-ischemic reperfusion phase, ATG inhibition (i.e., by the constitutive activation of mammalian target of rapamycin (mTOR), administration of the ATG inhibitors, and Atg7 knockdown) increases the neuronal damage and cognitive impairment." (PMID 30217100, 2018). "Consistent with a specific role of mTOR in the cognitive impairment induced by 5-HT6 receptor activation, rapamycin did not block the deficit in social recognition induced by the muscarinic receptor antagonist scopolamine (1.25 mg/kg s.c.)." (PMID 23027611, 2012). "EA stimulation of Shangxing (GV23) and Fengfu (GV16) can improve cognitive impairment in rats by suppressing oxidative stress and neuroinflammation; Another study found that EA downregulated LC3 II/LC3 I and autophagosomes, and upregulated the expression of p62, mTOR and Beclin-1 in MCAO rats." (PMID 39944540, 2025). "In the current study, we hypothesized that pathological concentrations of zinc could disturb the rapamycin-dependent mTOR/P70S6K and Nrf2/HO‐1 pathways, leading to detrimental effects on oxidative stress, tau hyperphosphorylation, and synaptic and cognitive impairment." (PMID 35197970, 2022). "However, phase II studies have not shown amelioration of ASD and cognitive deficits in individuals with TSC during mTOR inhibitor therapy." (PMID 33863288, 2021). "In fact, it has been demonstrated that restoring mTOR signaling with rapamycin ameliorates Aβ and tau pathology in several mouse models, preserves blood brain barrier (BBB) integrity, restores cerebral blood flow and brain vascular density and rescues cognitive deficits." (PMID 33343293, 2020). "In light of these findings, we hypothesized that chronic cannabis abuse during adolescence might induce a persistent non‐physiological activation of mTOR in adolescent brain that might lead to abnormalities in PFC maturation and cognitive impairment at the adult stage." (PMID 32329240, 2020). "Interestingly it has been shown that 5-HT6 signaling acts on the mTOR pathway and that 5-HT6 antagonists injected in adulthood could reverse the cognitive defects induced by early-life insults and normalize mTOR signaling pathway modifications." (PMID 23801939, 2013). "While we have not addressed the role of mTOR‐driven neuroinflammation or oxidative stress in our studies, these may represent important mechanisms through which mTOR inhibition ameliorates cerebrovascular dysfunction and cognitive impairment in the aging brain." (PMID 31693798, 2020). "In this study, we found that sevoflurane exposure activated the AKT/mTOR signaling rather than the AMPK/mTOR pathway, suggesting that AKT/mTOR‐mediated autophagy inhibition may be a pivotal process in sevoflurane‐induced cognitive impairment." (PMID 41405543, 2025). "However, the involvement of the mTOR/P70S6K pathway in zinc-induced oxidative stress, tau degeneration, and synaptic and cognitive impairment has not been fully elucidated in vivo." (PMID 35197970, 2022).
renal carcinoma (162 papers, 2008 to 2026). A carcinoma arising from the epithelium of the renal parenchyma or the renal pelvis. "Future research should focus on elucidating the molecular mechanisms underlying PI3K/AKT/mTOR pathway activation and identifying novel therapeutic targets to improve renal cancer diagnosis and treatment." (PMID 39092291, 2024). "Fumarate accumulation is well described as a driver of tumour aggressiveness in renal cancers that are fumarate hydratase-deficient, due to loss of heterozygosity of the enzyme or upregulation of the mammalian target of rapamycin (mTOR)." (PMID 36631900, 2023). "Everolimus and temsirolimus, mTOR inhibitors used for renal cancer, induced a marked loss of muscle mass in clinical settings." (PMID 34337889, 2021). "BHD-associated renal cancer shares some of the clinical features of the tuberous sclerosis complex syndrome, which on its own also regulate proteins involved in the mTOR pathway, and should be part of the differential diagnosis when considering BHD." (PMID 30326848, 2018). "FNIP degradation facilitated the replacement of FLCN by mTOR on the lysosomal surface, which, in turn, activated mTORC1 signaling associated with renal cancer development and progression." (PMID 28039480, 2017). "Degradation of FNIP2 leads to lysosomal dissociation of FLCN and subsequent lysosomal association of mTOR, which in turn promotes the proliferation of renal cancer cells." (PMID 28039480, 2017). "Mutations in the mTOR signaling pathway have been found in breast and renal cancer and thus mTOR has been targeted in several clinical trials." (PMID 25807077, 2015). "More recently, analysis of genome sequence of 750 cancer samples including renal cancer identified several point mutations in the C-terminus of mTOR." (PMID 25333702, 2014). "We therefore conclude that consistent overexpression of p-S6 protein in rat renal carcinomas caused by OTA in the present study implies modulation concerning mTOR signalling." (PMID 23105973, 2012). "On humans, two oncogenic mutations of mTOR have been reported so far in colorectal and renal carcinoma." (PMID 23167739, 2012). "Previous reports showed that loss of pVHL sensitized renal cancer cells to allosteric inhibitors of mTOR." (PMID 21791089, 2011). "The effect of mTOR inhibitors on angiogenesis is likely to have an important function in renal carcinoma, a highly vascularised tumour associated with a VHL-driven angiogenesis." (PMID 18797463, 2008). "Interestingly, the tumorigenic potential of FLCN-deficient renal cancer cells is inhibited by sirolimus, a mTOR inhibitor." (PMID 32751108, 2020). "Indeed, the intratumoral heterogeneity seen in renal carcinoma led to phenotypic diversity in the form of activating mutations in MTOR, which may predict for intrinsic resistance to drugs targeting the PI3K-MTOR pathway." (PMID 25546409, 2014). "We verified that NCKAP1 suppressed the proliferation and invasion of renal cancer cells via the PI3K/AKT/mTOR signaling pathway." (PMID 40141455, 2025). "A more recent study concluded that GpM triggers apoptosis in renal cancer cells by regulating the PI3K/AKT/mTOR signaling pathway." (PMID 38243957, 2025). "Another crucial function of the mTOR pathway is the promotion of angiogenesis within renal cancer tissues through the upregulation of VEGF." (PMID 40677703, 2025). "We further verified that NCKAP1 suppressed cancer cell growth and affected tumor development in renal cancer via the PI3K/AKT/mTOR signaling pathway." (PMID 40141455, 2025). "In this study, we demonstrated that NCKAP1 inhibited the growth and progression of renal cancer cells via the PI3K/AKT/mTOR signaling pathway, providing a molecular basis for its potential as a therapeutic target." (PMID 40141455, 2025). "Beyond its role in cell proliferation, mTOR signaling also regulates the epithelial-mesenchymal transition process, granting renal cancer cells enhanced invasive and migratory capacities." (PMID 40677703, 2025).